ENSG00000279284 ( gene)
Diseases named in the same sentence as ENSG00000279284 in open-access papers (continued):
Sharing a sentence is not in itself a finding about the gene and the disease.
Alzheimer disease (1 paper, 2021). A progressive, neurodegenerative disease characterized by loss of function and death of nerve cells in several areas of the brain leading to loss of cognitive function such as memory and language. "Heterogeneous depletion of microglia Beclin1, another autophagy‐related gene, also affected microglia activation and neuroinflammation in Alzheimer's disease mouse model." (PMID 34811872, 2021).
anemia (1 paper, 2025). A reduction in the number of red blood cells, the amount of hemoglobin, and/or the volume of packed red blood cells. "In the current study, the upregulation of Fanconi anemia complementation group D2 (FANCD2) was identified, which is reported as a crosslink repair gene." (PMID 40428293, 2025).
arterial diseases (1 paper, 2021). "This indicated that a tobacco-smoking-related gene (CHRNA3) and a thrombosis-related gene (F5) might play an essential role in PAD but not in other arterial diseases." (PMID 34943774, 2021).
Arthritis (1 paper, 2022). Inflammation of a joint. "CRY1 is a circadian clock-related gene that also plays a part in arthritis." (PMID 35886000, 2022).
autosomal dominant retinitis pigmentosa (1 paper, 2008). Autosomal dominant retinitis pigmentosa (RP) is an autosomally dominant inherited retinal dystrophy leading to progressive loss of the photoreceptors and retinal pigment epithelium and resulting in blindness usually after several decades. "The purpose of this project was to determine if mutations, including large insertions or deletions, in the recently identified RP31 gene topoisomerase I-binding arginine-serine rich (RS) protein (TOPORS), cause an appreciable fraction of autosomal dominant retinitis pigmentosa (adRP)." (PMID 18509552, 2008).
beta thalassemia (1 paper, 2021). Beta-thalassemia (BT) is characterized by deficiency (Beta+) or absence (Beta0) of synthesis of the beta globin chains of hemoglobin (Hb). "In addition to the sickle trait gene (HBB), our mapping strategies identified other members of beta globin gene cluster that cause various forms of beta-thalassemia (HBE1, HBD, HBG, and HBG2)." (PMID 34868193, 2021).
Bohring-Opitz syndrome (1 paper, 2026). "Background/Objectives: ASXL1 is a chromatin-associated gene implicated in both hematologic malignancies and neurodevelopmental disorders, including Bohring-Opitz syndrome (BOS)." (PMID 41751615, 2026).
Breast fibroadenoma (1 paper, 2021). "Breast fibroadenoma (FA) and phyllodes tumour (PT) often have variations of gene mediator complex subunit 12 (MED12) and mutations in the telomerase reverse transcriptase promoter region (TERTp)." (PMID 33046803, 2021).
breast tumours (1 paper, 2006). "Though we have not confirmed tumour suppressor activity of SKCG-1, however, the loss of expression of SKCG-1 in highly proliferative human Wilms and breast tumours suggest that it is a potential growth regulatory gene." (PMID 16622458, 2006).
congenital neutropenia (1 paper, 2022). "Patients with severe congenital neutropenia (SCN) have mutations in the gene for jagged 1 protein, (JAGN1)." (PMID 36034717, 2022).
cutaneous melanoma (1 paper, 2025). A primary melanoma arising from atypical melanocytes in the skin. "Furthermore, DIRAS2 has been identified as a tumor suppressor gene in cutaneous melanoma by inhibiting the Wnt/β-catenin signaling pathway and is associated with immune infiltration." (PMID 40083697, 2025).
cyst (1 paper, 2015). A sac-like closed membranous structure that may be empty or contain fluid or amorphous material. "The morphants of ttc4 and ttc25, a known cilia-related gene, additionally showed pronephric cyst formation." (PMID 25860617, 2015).
diabetic retinopathy (1 paper, 2023). "Several studies have indicated Socs1 as an inflammatory suppressor gene in ocular disorders, including diabetic retinopathy and uveitis 60,61." (PMID 37063422, 2023).
diarrheal disease (1 paper, 2026). The condition of having at least three loose or liquid bowel movements each day. "METHODS: Herein, we assessed the molecular variability of the intimin virulence gene (eae) in EPEC isolates, recovered from children under 5 years in a case-control study of diarrheal disease in Manhiça, southern Mozambique, from 2007 to 2010." (PMID 41877076, 2026).
diffuse large B-cell lymphoma (1 paper, 2013). "Following multiple-testing correction, one SNP in MSH3, a mismatch repair gene, showed an association with diffuse large B-cell lymphoma (OR: 1.91; 95% CI: 1.41–2.59; uncorrected p = 0.00003; corrected p = 0.010)." (PMID 24098683, 2013).
Duchenne muscular dystrophy (1 paper, 2021). Duchenne muscular dystrophy (DMD) is a neuromuscular disease characterized by rapidly progressive muscle weakness and wasting due to degeneration of skeletal, smooth and cardiac muscle. "QKI-5 also regulates the expression of Duchenne muscular dystrophy gene (DMD) in skeletal muscle by promoting the inclusion of its muscle-specific exon." (PMID 34616743, 2021).
endometrial adenocarcinoma (1 paper, 2020). "Besides, Dae-Shik Suh and his colleagues reported that LRIG2 was a tumor suppressor gene in endometrial adenocarcinoma and inhibited cell growth through regulating PI3K/AKT and EGFR." (PMID 32863771, 2020).
endometrioid carcinoma (1 paper, 2023). "ARID1A, a tumor suppressor gene encoding BAF250, a protein participating in chromatin remodeling, is frequently mutated in endometrium-related malignancies, including ovarian or uterine clear cell carcinoma (CCC) and endometrioid carcinoma (EMCA)." (PMID 38071325, 2023).
ependymoma (1 paper, 2018). A WHO grade II, slow growing tumor of children and young adults, usually located intraventricularly. "We also found RAD51, another DNA repair gene, was up-regulated in supratentorial and infratentorial ependymomas." (PMID 29416789, 2018).
erythroleukemia (1 paper, 2021). Acute erythroid leukemia characterised by the presence of at least 50% erythroid precursors and at least 20% myeloblasts in the bone marrow. "Since FLI1 activation was frequently detected in erythroleukemias, it is therefore possible that this TF acts as an oncogene in erythroleukemias, but functions as a tumor suppressor gene in megakaryocytic leukemias." (PMID 33717090, 2021).
fibrosis (1 paper, 2017). the formation of excess fibrous connective tissue in an organ or tissue in a reparative or reactive process. "When RNA from kidney poles was analyzed, Grem1 levels were significantly increased in wild-type mice, consistent with previous data showing that Grem1 is a fibrosis-associated gene." (PMID 28100499, 2017).
follicular thyroid cancers (1 paper, 2020). "This contrasts to reports that NR4A3 acts as a tumor suppressor gene in lymphoreticular and follicular thyroid cancers." (PMID 32867110, 2020).
gastric MALT lymphoma (1 paper, 2022). "Although vacA is a potent immune gene, given the fact that this protein causes apoptosis, it does not appear to play a significant role in the development of gastric MALT lymphoma." (PMID 34980267, 2022).
gastric tumors (1 paper, 2016). "In this work, we identify GPC3 as a potential metastasis suppressor gene that controls cellular mechanisms of invasion and metastasis in gastric tumors." (PMID 27259271, 2016).
HCMV infections (1 paper, 2022). "HCMV infections were performed with a dual tagged Merlin HCMV strain which expresses mCherry linked to UL36 (an immediate early protein) and UL32-GFP fusion (pp150 a true HCMV late gene)." (PMID 36591233, 2022).
Hepatic steatosis (1 paper, 2015). Steatosis is a term used to denote lipid accumulation within hepatocytes. "Moreover, its antioxidant activities were also able to reduce the high cholesterol associated hepatic steatosis and inflammation through upregulation of the Bcl2a1a antiapoptotic gene." (PMID 26074993, 2015).
Hydrocephalus (1 paper, 2015). Hydrocephalus is an active distension of the ventricular system of the brain resulting from inadequate passage of CSF from its point of production within the cerebral ventricles to its point of absorption into the systemic circulation. "Recent studies have shown that the Lhx9 homeobox gene controls pineal gland development and prevents postnatal hydrocephalus." (PMID 26321920, 2015).
hypopharyngeal carcinoma (1 paper, 2023). Carcinoma, predominantly squamous cell, arising from the epithelial cells of the hypopharynx. "Similarly, in hypopharyngeal carcinoma, we found that KRT17 acts as a cancer suppressor gene; this effect may be related to the tissue specificity of KRT17." (PMID 36765563, 2023).
hypophosphatemia (1 paper, 2021). Lower than normal levels of phosphates in the circulating blood. "In contrast, hypophosphatemia enhances Nhdec2 expression in NPT2aKO osteocytes and phosphate treatment of Ocy454 cells decreases expression of this mineral resorption gene." (PMID 34043707, 2021).
idiopathic scoliosis (1 paper, 2019). A scoliosis with no known cause. "For example, a recent study reveals that the deficiency of a cilia-related gene, pkd2zko977a, in zebrafish embryos results in phenotypes similar to those of human idiopathic scoliosis." (PMID 31831591, 2019).
influenza (1 paper, 2016). An acute viral infection of the respiratory tract, occurring in isolated cases, in epidemics, or in pandemics; it is caused by serologically different strains of viruses (influenzaviruses) designated A, B, and C, has a 3-day incubation period, and usually lasts for 3 to 10 days. "Many studies on influenza pathogenesis in mice were performed in classical laboratory strains which carry a mutation in the influenza resistance gene Mx1 first described in the A2G mouse strain." (PMID 26921172, 2016).
invasive lobular carcinoma of the breast (1 paper, 2009). "In summary, our findings suggest that ADAM33 is a novel tumour suppressor gene that may be useful as a molecular marker for invasive lobular carcinoma of the breast." (PMID 19267929, 2009).
laryngeal squamous cell carcinoma (1 paper, 2025). A squamous cell carcinoma that arises from the larynx. "Additionally, as a tumor metabolic regulatory gene, SKA3 can inhibit the ubiquitination and degradation of polo-like kinase 1 (PLK1) protein, resulting in the upregulation of glycolytic enzymes and enhanced glycolysis in laryngeal squamous cell carcinoma." (PMID 41298345, 2025).
Lissencephaly (1 paper, 2022). A spectrum of malformations of cortical development caused by insufficient neuronal migration that subsumes the terms agyria, pachygyria and subcortical band heterotopia. "WDR47 (WD repeat-containing protein 47, MIM 615734), sharing structural homology with lissencephaly gene LIS1 (PAFAH1B1), participates in core microtubule-mediated processes, including neural stem cell proliferation, radial migration, and growth cone dynamics." (PMID 36277487, 2022).
lung neoplasm (1 paper, 2019). A benign or malignant, primary or metastatic neoplasm involving the lungs. "miRNAs have been found as a tumor suppressor gene and lung neoplasms." (PMID 31921290, 2019).
mismatch repair deficiency (1 paper, 2024). "The mismatch repair gene MSH3 has become a major focus for therapeutic development, as unlike other mismatch repair genes, nullizygosity for MSH3 does not cause malignancies associated with mismatch repair deficiency." (PMID 38387080, 2024).
multiple endocrine neoplasia type 1 (1 paper, 2010). An autosomal dominant tumor predisposition syndrome caused by pathogenic variants in the MEN1 gene, characterized by an increased risk of tumors of the parathyroid glands, pituitary gland, and foregut neuroendocrine tumors (most commonly pancreatic islet cells). "The multiple endocrine neoplasia type I gene functions as a tumor suppressor gene in humans and mouse models." (PMID 21124979, 2010).
multiple sclerosis (1 paper, 2023). A progressive autoimmune disorder affecting the central nervous system resulting in demyelination. "Multiple sclerosis is a fairly common autoimmune demyelinating disease; EVI5L may therefore play an important role in cellular immunity as an immune-related gene." (PMID 36635413, 2023).
myopia (1 paper, 2025). "With the progression of myopia, the proinflammatory macrophages and their expression of the hypoxia-responsive gene Car1 also increased gradually." (PMID 41330940, 2025).
neuritis (1 paper, 2016). A neuropathy arising from inflammation of one or more nerves. "It was also reported as a retinoic acid-responsive gene concerned with prenatal development and neuritis growth." (PMID 27571066, 2016).
ovarian serous carcinoma (1 paper, 2010). "RSF1, a chromatin-remodeling gene, was identified as a potential oncogene in ovarian serous carcinoma." (PMID 20932292, 2010).
pancreatic neuroendocrine tumor (1 paper, 2016). Pancreatic endocrine tumor, also known as pancreatic neuroendocrine tumor (PNET), describes a group of endocrine tumors originating in the pancreas that are usually indolent and benign, but may have the potential to be malignant. "Taken together, these observations demonstrate that CYR61 acts as a tumor-promoting gene in pancreatic neuroendocrine tumors." (PMID 26625209, 2016).
pituitary carcinoma (1 paper, 2020). A primary or metastatic malignant neoplasm affecting the pituitary gland. "In their study, they suggest that miR-17-5p is involved in pituitary carcinoma metastasis, attenuating target genes such as PTEN, a tumour suppressor gene, and TIMP2, involved in inhibiting the degradation of the extracellular matrix and basement membrane." (PMID 32316225, 2020).
prostate tumor (1 paper, 2021). "Transcriptomic profiling revealed a distinct gene expression profile of MCs isolated from prostate tumor regions, including the downregulation of SAMD14, a putative tumor suppressor gene." (PMID 33799802, 2021).
retinal diseases (1 paper, 2020). "Decidual protein induced by progesterone (DEPP) has been identified as a hypoxia-responsive gene that may be part of cellular pathways such as autophagy and connected to retinal diseases." (PMID 31963726, 2020).
T-cell acute lymphoblastic leukemia (1 paper, 2013). Acute lymphoblastic leukemia of T-cell origin. "In this chromosome locus, BCL11B may act as a tumor-suppressor gene in T-cell acute lymphoblastic leukemia." (PMID 24422944, 2013).
thymoma (1 paper, 2017). A neoplasm arising from the epithelial cells of the thymus. "In pTECs from thymomas, senescence became recognizable after 15 days in culture, and RNA expression of p16INK4A (a senescence-associated gene) started to rise progressively on day 10 to 15 after surgery and lasted till the 3rd to 5th passage." (PMID 29163772, 2017).
triple-negative breast carcinoma (1 paper, 2019). An invasive breast carcinoma which is negative for expression of estrogen receptor (ER), progesterone receptor (PR), and human epidermal growth factor receptor 2 (HER2). "Although decorin is regarded as the “endogenous guardian” and biglycan acts as a danger signal in cancer, asporin acts as an oncogene in some types of cancer (breast, pancreatic, colorectal, gastric, and prostate), but as a tumor suppressor gene in triple-negative breast cancer." (PMID 31608236, 2019).
tumor (793 papers, 1995 to 2026). "DAPK-1 is a tumor suppression gene and induces apoptosis in several cells associated in various diseases." (PMID 41189711, 2025). "Of note, although the proportion of trunk mutations was significantly less than branch mutations in L-FLAC patients, driver gene mutations (oncogene and tumor-suppression gene) were significantly enriched in trunk mutations (P = 0.038; Wilcoxon rank-sum test)." (PMID 38831114, 2024). "GSDMC was first discovered as a tumor‐associated gene in 2004, which is closely associated with melanoma metastasis." (PMID 37125240, 2023). "E-cadherin is a vital tumor development suppressor gene, and the loss of this protein adhesion can turn benign tumors into aggressive malignant tumors." (PMID 37762330, 2023). "For example, TSC2 (tuberous sclerosis complex 2) was a tumor suppression gene that was reported that specific mutations of this gene led to the development of renal and extra-renal tumors in mice." (PMID 37582720, 2023). "The underlying mechanism is that TPM is a class II tumor-suppressor gene, and its gene sequence structure is complete, but its expression is insufficient or not expressed due to downregulation or silencing in transcription or translation." (PMID 37686101, 2023). "The retinoblastoma susceptibility gene (Rb1), as a tumor repressor gene, has critical effects on multiple cellular processes, such as ferroptosis, apoptosis, and DNA repair." (PMID 36851083, 2023). "KEAP1 is regarded as a tumor-suppressive gene, and research has shown that a KEAP1 loss-of-function mutation promotes tumor growth." (PMID 36909198, 2023). "ccRCC represents 75% of all RCC cases, and about 80% of ccRCC cases harbor mutations of the tumour-suppressive gene, VHL." (PMID 35461314, 2022). "In fact, DUSP6 is implicated as a tumor suppressor gene in PC and, specifically, its expression is suppressed in MIA PaCa-2 cells through intron 1 hypermethylation." (PMID 34439102, 2021). "Authors concluded that Setd2 can potentially act as a tumor suppressor gene in lung adenocarcinoma, since its deficiency promoted shifting of the tumor grade." (PMID 34781949, 2021). "One of the PNenGs, IGF2R, was a tumor suppressor gene, with a high frequency of loss-heterozygosity (LOH) and protein expression in diverse types of malignant cancer." (PMID 34221990, 2021). "Although these data indicated Ctcf behaved as a tumor suppressor gene, which was also supported by somatic mutation burden of CTCF in a recent human pan-cancer study, contradictory results were seen in other models regarding the CTCF/MYC regulation axis." (PMID 31127282, 2019). "This is the first time PTEN has been directly connected with human B cell dysfunction outside of the cancer field where PTEN is a well-described tumor suppressor gene whose mutation or deletion plays a role in a variety of sporadic human cancers." (PMID 30792481, 2019). "The OIS is a robust and sustained antiproliferative response brought by oncogenic signaling resulting from an activating mutation of an oncogene, or the inactivation of a tumor-suppressor gene." (PMID 29435113, 2018). "In numerous contexts, miR-494 functions as tumor suppressor gene and has been linked to the induction of senescent phenotype in normal cells but in other contexts it correlates with tumor aggressiveness and progression." (PMID 29951371, 2018). "In this study we focused on the lncRNA, prostate cancer associated transcript 29 (PCAT29), a putative tumor suppressive gene." (PMID 28467474, 2017).